IL1B (interleukin 1 beta)
Diseases named in the same sentence as IL1B in open-access papers (continued):
Sharing a sentence is not in itself a finding about the gene and the disease.
infection (continued). "On the other hand, in monocytes, activation of TLR7 by HCV virions was associated to activation of the inflammasome pathway, promoting the secretion of IL-1β and IL-18 in a NLRP3-dependent and infection independent pathway." (PMID 27610098, 2016). "We show that IL-17-mediated inflammation correlated with production of inflammatory cytokines (such as IL-6, IL-1β and TNF-α) that were profoundly increased at the early times upon infection including CLP treatment." (PMID 27389701, 2016). "In contrast to the release of pro-inflammatory cytokines TNFα, IL-1β and IL-6, the release of FKN increased from 24 h up to 72 h post infection." (PMID 26739172, 2016). "The results demonstrate that the level of mRNA expression of IL-6, IL-8, IL-10, COX-2, IL-1β, IL-18, and TNF-α were significantly upregulated in peripheral blood monocytes following infection with H. parasuis for 3 or 6 h (p < 0.01)." (PMID 27502767, 2016). "The infection induced increased expression of TNF-α, IL-1β and IL-10 in both WT and SG−/− mice, but the cytokine levels were significantly lower in the SG−/− mice." (PMID 27267469, 2016). "Protein concentrations of IL-6, IL-1β, TNF-α and IL-10 were consistently the highest in secondary infections with serotype 4 followed by serotype 3." (PMID 27034012, 2016). "The levels of IFNγ,IL-12/IL-23 p40, IL-1β, CXCL1/KC as well as the expression of CXCR2 wereincreased in the lung of M-TNFR1 KO as compared with TNFR1 KO 3 weekspost-infection, and further increased in both groups at 4–5 weeks." (PMID 26931771, 2016). "Seven days post infection, CS + IAV mice had increased mRNA expression of pro-inflammatory chemokines (CCL-2, CXCL-2), cytokines (GM-CSF, TNF-α, IL-1β, IL-6) and proteases (MMP-12) compared to sham + IAV + diluent mice." (PMID 26877172, 2016). "At the early stages of infection, TNF-α, IL-1β, IL-6, and IL-8 pro-inflammatory cytokines are produced and stimulate immune cells leading to activation of an inflammatory cascade." (PMID 28066425, 2016). "The results of this study demonstrate that HGPg infection not only induces NLRP3 upregulation, but also enhances active caspase-1 and mature IL-1β expression in HGFs." (PMID 28083517, 2016). "First, the inhibition of Akt and p70S6K phosphorylation in HGFs through pretreatment with inhibitors, or infection with DN-Akt, abolished HGPg-induced SREBP-1c and NLRP3 expression, as well as IL-1β secretion." (PMID 28083517, 2016). "The expression of proinflammatory cytokine IL-1β and the neutrophil chemokine CXCL1 were higher in 5b WT-infected mice throughout the course of infection." (PMID 27046446, 2016). "The systems biology analysis identified multiple immune system and inflammation molecules (e.g., STAT3, STAT1, CEBPB, JUN, IGF1, SPP1, NFKB2, IL-1β, and CSF1) as master regulators that are activated upon infection." (PMID 26865111, 2016). "Three days post infection, CS + IAV mice had increased mRNA expression of pro-inflammatory chemokines (CCL-2, CXCL-2), cytokines (GM-CSF, TNF-α, IL-1β, IL-6) and proteases (MMP-12) compared to sham + IAV + diluent mice." (PMID 26877172, 2016). "We observed that infection significantly upregulates the secretion of cytokines TNF-α, IL-1β, IL-8, MCP-1, MMP, oxidative stress, transendothelial permeability, and LDL uptake." (PMID 27582738, 2016). "Previous studies have shown that the pro-inflammatory cytokine IL-1β has a crucial role in host defenses against group B streptococcus (GBS), a frequent human pathogen, by recruiting neutrophils to infection sites." (PMID 27509078, 2016). "Consistent with this idea, overstimulation of NOD2 at the same time as infection with S. Typhimurium leads to a CARD9- and NOD2-dependent decrease in pro-IL-1β expression." (PMID 27670879, 2016). "Consistent with the data of expression of inflammatory genes in our in vitro experiment, infection with LV-VNN1 increased the plasma concentrations of TNF-α, IL-1β, and IL-6 by 32.8%, 31.8%, and 56.5%, respectively." (PMID 27281478, 2016).
infection (continued). "Suppression of IL-1β, IFN-γ as well as IL-6 by the Riboflavin and CIP or AZM treated macrophages at late stage of infection further confirms their anti-inflammatory nature." (PMID 27932936, 2016). "It is suggested that the ensemble of CD8-positive signals in tissues was associated with the increased level of proinflammatory cytokines (IL1β and IL6) during both GPV and TMUV infection." (PMID 27150912, 2016). "Rapid and more-sustained elevations in IL-1ra, MIP-1α, IL-5, IL-10 and IL-17 levels were followed by IL-1β, IL-2, IL-7, IL-9, IL-12, IL-15, IFN-α2, MIP-1β, FGF-2 and GM-CSF at over 2 months post-infection, and accompanied by the recovery of CD4+ cells." (PMID 27830756, 2016). "The temporal expression patterns of MR, IL-1β and TNF-α mRNAs were analyzed in the liver, spleen, kidney and intestine post of infection with Aeromonas sobria." (PMID 25988382, 2015). "Ciaramella and co-workers also found that infection of human monocytes with MTB induced caspase-1-mediated apoptosis as well as TNFα and IL-1β production." (PMID 25887904, 2015). "We therefore considered it of interest to examine the impact of MyD88 deficiency on the concentrations of proinflammatory cytokines (TNF-α, IL-1β, IL-6) and CXC chemokines (KC, MIP-2) after infection with D39 or D39Δcps." (PMID 25700108, 2015). "In contrast, 24 weeks of infection induced new changes in other inflammatory molecules with reduced KC, MCSF, enhancing GM-CSF, IFNγ, IL-1β, IL-13, IL-4, IL-13, lymphotactin, RANTES, and also an increase in select inflammatory molecules." (PMID 26619277, 2015). "Eighteen cytokines were elevated >2-fold relative to controls at 12 weeks of infection, including CD 30L, Fas ligand, Fractalkine, GCSF, IFN-γ, IL1-β, IL4, IL10, IL12p40/p70, IL12p70, IL17, I-TAC, Lymphotactin, MCP-1, MCSF, MIG, MIP-1α, and TIMP-2." (PMID 26079509, 2015). "The local innate immune response of mammary glands was swiftly activated after S. aureus inoculation during the initial stage of infection, characterized by up-regulation of gene expression of TLR2, NOD2, TNF-α, IL-1β, IL-6, and CXCL1." (PMID 25990971, 2015). "The last group of genes included IL-1β, CXCLi2 (IL-8), AVD, IRG1, iNOS, ExFABP, TGM4 and SAA whose expression in HD11 cells increased after the infection with S. Enteritidis." (PMID 26380970, 2015). "To examine the role of the proinflammatory property of CP in the increased murine mortality, we administered antibodies against IFN-γ, IL-1β, or TNF-α at 2 h post infection and compared the murine mortality." (PMID 26147796, 2015). "As a result TLR activation upregulates the transcription of proinflammatory cytokines including IL-1β, TNF-α and IL-6 which are essential for the recruitment of immune cells to the site of infection and controlling MTB infection." (PMID 25312698, 2015). "Significant up-regulation of proinflammatory cytokines such as IL1B, IL6, and IL8 was observed, correlating with protein levels, infection status and histopathological findings." (PMID 26018580, 2015). "Instead, we found that the SaeRS TCS plays a significant role in the production of not only IFN-γ but also IL-1β, IL-6, MIP-2, and IL-17A/F during murine infection." (PMID 26147796, 2015). "According to previous studies, an appropriate amounts of cytokines, such as IL-1β, IL-6 and TNF-α, is beneficial in response to infection, but overstimulation of the immune system can have detrimental effects." (PMID 26635958, 2015). "Consistent with the role of STAT3 in IL-21-mediated IL-1β expression, Il1b mRNA was also lower in lungs from Stat3−/− than from WT mice after PVM infection." (PMID 26269257, 2015). "Infection of the mouse A/E pathogen C. rodentium has been shown to activate the NLRP3 inflammasome, which is critical for the production of IL-1β and IL-18 and protection in mouse macrophages." (PMID 26332984, 2015).
infection (continued). "To validate transcriptional changes in iHOs after infection with S. Typhimurium SL1344, we carried out further microinjections with PBS or SL1344 and measured the mRNAs for IL-8, IL1B, IL23A, TNF, and CXCL2 with quantitative assays." (PMID 25964470, 2015). "WNV-induced expression of pro-inflammatory cytokines such as IL-1β and TNF modulate BBB permeability, facilitate leukocyte trafficking into the brain, activate glial cells, and mediate neuronal death after infection." (PMID 26392176, 2015). "By contrast, DRSA infection had little effect on pulmonary expression of TNF-α and IL-1β in SW-EXE mice, although the baseline levels of the two cytokines were already higher than in No-EX mice." (PMID 26542343, 2015). "This Vero-derived supernatant displayed a strong IL-1β-inducing activity that was unaltered by ADE, despite concurrent enhancement of infection by antibody." (PMID 26301593, 2015). "IL-1β and IL-18 levels were measured in the bronchoalveolar lavage fluid (BALF) or serum obtained from infected mice 72 hours or 6 days post-infection." (PMID 25768794, 2015). "HD11 macrophages responded to the infection with the wild type S. Enteritidis and SPI2, phoP and aroA mutants by an increase in transcription of inflammatory genes such as IL-1β, CXCLi2 (IL-8), ExFABP, AVD, IRG1 or iNOS." (PMID 26380970, 2015). "In contrast, when the cells were pretreated with EM900 before infection and treated with EM900 after infection, the infection-induced secretion of IL-1β at 72 h after infection was reduced compared with the vehicle-treated cells." (PMID 26462747, 2015). "Il1b showed modest upregulation in joints of Il10-/- and DKO mice upon infection, compared to uninfected controls, but differences between these strains and joints of infected B6 and Mir155-/- mice did not achieve statistical significance by ANOVA." (PMID 26252010, 2015). "Palmitate-induced increases of IL1β and IL6 mRNA levels were still detected after the infection of Ad-SIRT3LF or Ad-SIRT3SF." (PMID 25915406, 2015). "Using a mouse viral FH model by infection with murine hepatitis virus strain-3 (MHV-3), we observed a significant macrophage induction and the serum and liver massive accumulation of IL-1β." (PMID 26367131, 2015). "We observed a significant down-regulation of TNF-α, IL-1β, IL-6 and IFN-γ, compared with the infection control, by ELISA and qPCR." (PMID 26405764, 2015). "Wild-type RB50 induced lower levels of IL-1β than RB50ΔclpV in the lungs and spleens of Rag1-/- mice by day 21, indicating that the T6SS suppresses IL-1β production during infection (p<0.05)." (PMID 26485303, 2015). "Homogenates of kidneys from CD11cΔSyk mice showed higher levels of IL-6, KC, MIP-1α, IL-1β, TNF, IL-1α and MCP-3 at days 1 or 2 post-infection when compared to control mice." (PMID 25033445, 2014). "Challenge with the respiratory pathogen induced an early increase (12 hours post-infection) of TNF-α, IL-1β and IL-6 levels and a late increase of IFN-γ (48 hours post-infection) in BAL and serum, in both experimental groups." (PMID 24691464, 2014). "Here, in vitro infection showed that both isolates induced a strong production of NO and the cytokines TNF-α, IL-6, IL-1α, IL-1β, and IL-10." (PMID 24886263, 2014). "During infection, monocytes produce pro-inflammatory molecules, such as tumor necrosis factor-alpha (TNF-α), interleukin-1 beta (IL-1β), IL-6, and nitric oxide (NO) to destroy pathogens." (PMID 25329066, 2014). "WNV-induced expression of pro-inflammatory cytokines such as IL-1β and TNF regulate leukocyte trafficking into the brain, and neuronal death after infection." (PMID 24750819, 2014). "Macrophages have been reported to be the major source of interferon α/β, which plays a key role in viral clearance, and are important sources of IL-1β, IL-6 and TNF-α, which are responsible for the acute phase response to the infection." (PMID 25232724, 2014).
infection (continued). "We confirmed that anti-TNF-α and anti-IL-1β neutralizing antibodies inhibited the effect of recombinant TNF-α and IL-1β on HCVpp infection." (PMID 24259385, 2014). "Infection of cultured feline macrophages by the related lentivirus, feline immunodeficiency virus (FIV), also resulted in the prompt induction of IL-1β." (PMID 24886384, 2014). "Moreover, Trichuris infection was associated with increased plasma levels of pro-inflammatory (IL-1β and IL-17α), anti-helminthic (IL-13) and regulatory (IL-10) cytokines, which closely correlated with each other; showing a mixed cytokine response to infection with Trichuris." (PMID 24675895, 2014). "In serum 24 hours after infection, TNF-α, MIP-2, and Il-1β levels were low but KC was readily detectable and higher in Nlrc4−/− mice compared to Casp1−/−Casp11−/− mice." (PMID 25232720, 2014). "In the present study, we examined the levels of TNF, IL-1β, IL-6, IL-8, and CCL5 in the supernatants of HTNV-infected HUVECs at 48 h post infection using ELISA." (PMID 24714064, 2014). "Intranasal infection of BALB/c mice with the BsaK mutant displayed a strongly decreased mortality, lower bacterial loads in organs, and reduced levels of IL-1β, myeloperoxidase and neutrophils in bronchoalveolar lavage fluid." (PMID 24626296, 2014). "On other hand, monocyte and neutrophil recruitment, through KCs derived IL-6, IL-12, IL-1β, TNF-α, NO and chemokines (MIP-1α/β, MCP-1, MIP-2) limits the infection." (PMID 24976841, 2014). "At later stages of infection, RRV-infected OA hOBs showed significantly increased IL-6, IL-1β and CCL2 expression compared to healthy infected controls." (PMID 25407789, 2014). "Here, we provided the basic data of expression pattern and histological distribution of NLRP3, IL-1β and TNF-α in lung and brain during infection in BALB/c mice by H9N2 avian influenza virus strains with only a difference at site 627 in PB2." (PMID 25547136, 2014). "As expected, due to the expression of a large number of NF-κB inhibitors, infection of A549-NF-κB-LUC cells with VACV Copenhagen inhibited NF-κB reporter activity in response to TNF-α and IL-1β stimulation." (PMID 24371075, 2014). "IL-1β, TNFα, MCP-1 and IL-8 mRNA are increasingly expressed in hepatocytes as early as 6 h after infection with H. hepaticus." (PMID 24932686, 2014). "Serological analyses showed elevated mean serum levels of IL-6, IL-1β, and CRP in the MRSA-infected animals during the early phases of infection." (PMID 25184249, 2014). "We found that Mtb HN878-infection of TLR-2−/− lung DCs, had a dramatic impairment in IL-1β production when compared to infection of B6 DCs, and coincided with low IL-17 production in DC: lung cell co-cultures." (PMID 24831696, 2014). "Both VK627 and rVK627E infection can active the expression of NLRP3, IL-1β and TNF-α in the lung and brain of BALB/c mice at different levels and this also improved that site 627 in PB2 takes part in the virulence of H9N2." (PMID 25547136, 2014). "In infected groups, the expression level of NLRP3, IL-1β and TNF-α increased rapidly at 3 dpi and VK627 infection were higher than that of rVK627E." (PMID 25547136, 2014). "Both IL-1β and TNF-α increased HCVpp (strain H77) infection of polarized HepG2.CD81 cells, whereas IFN-γ reduced infection in a dose-dependent manner." (PMID 24259385, 2014). "CK1 induced high pulmonary levels of proinflammatory cytokine IL-1β, IL-6 and chemokine RANTES at all studied time points after infection." (PMID 25232731, 2014). "Infection with C. rodentium produced significant increases in the hepatic mRNA expression of TNFα, IL6, IL1β, serum amyloid A (SAA), and serum amyloid P (SAP), indicative of a hepatic inflammatory response." (PMID 24707356, 2014). "Infection of bovine epithelial cells and monocytes with rBRSVΔSH, in vitro, resulted in an increase in apoptosis, and higher levels of TNF-α and IL-1β compared with cells infected with parental, wild-type (WT) rBRSV." (PMID 24700100, 2014).
infection (continued). "IAV infection significantly increased the levels of all tested proinflammatory cytokines (IL-1β, IL-6, IL-2, TNF-α, IFN-α, IFN-β and IFN-γ) in lung homogenates between 1.2- and 13.7-fold relative to the baseline (before infection)." (PMID 24865588, 2014). "Paired samples of Bronchiolo-alveolar lavage fluid (BALF) and blood from each subject were analysed for putative biomarkers of infection: Cellular (TREM-1, CD11b and CD62L) and soluble (IL-1β, IL-6, IL-8, sTREM-1, Procalcitonin)." (PMID 25289689, 2014). "At euthanasia, spleen MC of the infection group had produced significantly less IFN-γ, TNF-α, IL-1β, IL-6, IL-8 and IL-12p40 than MC of the other groups." (PMID 25252649, 2014). "Our results demonstrated that higher levels of IL-12, IL-1β, IL-4 (Th2) and IFN-γ (Th1) were produced following infection of BMDCs with the recombinant virus than with the control virus." (PMID 25420583, 2014). "In contrast, we observed significantly less production of IL-12p40, IL-12p70, IL-1α, IL-1β, IL-17A, CXCL1, CCL2 and CCL5 in the lungs as the infection progressed." (PMID 25119981, 2014). "The results showed that the expression level of NLRP3, IL-1β and TNF-α changed in the lung and brain of BALB/c mice after infection by VK627 and rVK627E." (PMID 25547136, 2014). "In contrast, infection with ECTV and ECTV-Δ005 prevented transcriptional upregulation of TNFα, IL-1β, and IL-6." (PMID 25122471, 2014). "WNV infection resulted in a 3- to 10-fold increase in the mRNA expression of cytokines such as IL-1β, TNF and IFNγ in the brains of WT mice at day 8 after infection compared to corresponding mock-infected mice." (PMID 24750819, 2014). "Similar to the mRNA expression, protein levels of IL-1β, TNF, IL-6, IFNγ, and IL-1α were also significantly elevated in the brains of db/db mice when compared to WT mice at day 8 after infection as measured by the multiplex immunoassay (P <0.05)." (PMID 24750819, 2014). "We also observed remarkable increases in IL-1β, IL-2, IL-10 and TNF-α at 7 dpi after which IL-1β and IL-2 dropped to pre-infection levels, IL-10 and TNF-α decreased to lower levels than pre-infection levels." (PMID 24465897, 2014). "The other investigated pro-inflammatory cytokines were low (IL-6 on day 3 and IL-1β and IL-6 on day 7) or undetectable (IL-1β and IL-12p40 on day 3) during MOI 1 infection." (PMID 25386849, 2014). "As the lung and brain showed significant differences in these two H9N2 avian influenza virus strains infection, we chosen to detect the expression patterns of NLRP3 and its related cytokines of IL-1β and TNF-α." (PMID 25547136, 2014). "On the other hand, mRNA transcripts of IL-1β and COX-2 were upregulated in mice pretreated with P1G10 after infection." (PMID 24757289, 2014). "Infection increased the levels of pro-inflammatory cytokines IL-6 and IFN-γ in WT mice and as well IL-1β in Nlrp3−/− mice." (PMID 24312491, 2013). "In the IB3-1 CF cellular model, NF-κB dependent genes, including the gene coding for the proinflammatory protein IL-8, generally are activated following infection with P. aeruginosa, or treatment with TNF-α or IL-1β." (PMID 23935691, 2013). "To define potential mechanisms for the observed detrimental overcompensation of IL-1β in treated WT mice, we examined the possibility that excessive infiltration by macrophages may have contributed to the damage to the epithelial barrier, in addition to infection." (PMID 24312491, 2013). "The peripheral immune system normally produces various pro-inflammatory cytokines, including interleukin-1β (IL-1β), IL-6 and tumor necrosis factor-α (TNF-α) during infection." (PMID 24137231, 2013). "Upon infection with E. papillata, there was a significant increase in the mRNA expression of TNF-α, iNOS, IFN-γ, and IL-1β." (PMID 24367242, 2013).